CDKN2A (cyclin dependent kinase inhibitor 2A)
Diseases named in the same sentence as CDKN2A in open-access papers (continued):
Sharing a sentence is not in itself a finding about the gene and the disease.
lung adenocarcinoma (71 papers, 2004 to 2025). A carcinoma that arises from the lung and is characterized by the presence of malignant glandular epithelial cells. "This highlights the importance of reinforcing the clinical management and follow-up of patients with CDKN2A deficiency, particularly within the subset of stage I lung adenocarcinoma." (PMID 39323996, 2024). "We sought to characterize the genomic landscape associated with CDKN2A deletion in EGFR/ALK- lung adenocarcinoma specimens using the Foundation Medicine genomic dataset." (PMID 35739333, 2022). "Collectively, lung adenocarcinoma patients with lower risk score or higher CDKN2A expression levels present more immune cells in TIME, suggesting an activated immune phenotype that results in longer overall survival." (PMID 35004299, 2021). "The survival curve analysis showed that lung adenocarcinoma patients with high levels of CDKN2A expression are associated with poorer survival rates." (PMID 29285217, 2017). "Both cell lines have 2-copy loss of the most commonly deleted genome segment in human lung adenocarcinoma—which contains the genes CDKN2A/B/B-AS1 (one focal, the other larger CNA)." (PMID 26560147, 2015). "The CDKN2A gene, for which expression suppressions were reported as major causative events in lung adenocarcinoma, DNA methylation should be the dominant cause of the transcriptomic aberrations, following genomic alterations." (PMID 25378332, 2014). "Although mutations of RB1 are rare in lung adenocarcinomas, CDKN2A, the gene encoding p16INK4a the upstream activator of the pRB pathway is a frequently targeted for mutation." (PMID 23936539, 2013). "The homozygous deletion form of CDKN2A is common in patients with lung adenocarcinoma, with a prevalence of 22% in Chinese population; TCGA data of people of European descent shows a mutation frequency of 15%; whereas Korean data shows only a 4% prevalence of CDKN2A mutations." (PMID 39323996, 2024). "For the lung adenocarcinoma (LUAD) patients, the mutational rate in DACH1 was higher in the higher-score individuals, while CDKN2A and SMARCA4 were higher in the lower-score individuals." (PMID 41431699, 2025). "Data were analyzed on 2532 cases of lung adenocarcinoma with information on CDKN2A expression, staging, and survival." (PMID 39323996, 2024). "The amplifications of MYC, YAP1, and MMP13, as well as the deletion of CDKN2A/B, contributed to LC-BrMs originating from lung adenocarcinoma." (PMID 39593114, 2024). "We validated our findings in surgically resected specimens from 20 primary lung adenocarcinoma patients by immunofluorescence staining and revealed a positive correlation between frequencies of CDKN2A+ senescent cells and CD73+CD68+ macrophages." (PMID 38323313, 2024). "CDKN2A/B homozygous deletion (CDKN2A/BHD) was a common event and associated with poor outcomes in lung adenocarcinoma (LUAD)." (PMID 35253368, 2022). "Genomic data analyses evidenced that EGFR and KRAS mutations, the most common aberrations in lung adenocarcinoma, are extremely rare in pure SCC, while alterations in the FGFR kinase family, PIK3CA, CDKN2A and RB1 pathways are common." (PMID 35743191, 2022). "CDKN2A has been reported to promote lung adenocarcinoma invasion and is correlated with poor prognosis." (PMID 35035831, 2022). "The correlation between CDKN2A and ICI key targets adjusted by tumor purity using TIMER was analyzed to investigate the potential role of CDKN2A in ICI treatment of lung adenocarcinoma." (PMID 35004299, 2021).
lung adenocarcinoma (continued). "These are among the most common CNAs seen in human lung adenocarcinoma, with CDKN2A being involved in 43% of cases." (PMID 26560147, 2015). "Based on the results of our analyses, four loci that are very strong candidates for a DNA methylation panel aimed at early lung adenocarcinoma detection have been identified: CDKN2A EX2, CDX2, HOXA1 and OPCML." (PMID 17967182, 2007). "Lastly, in patients with stage IV lung adenocarcinoma, those with CDKN2A deletions in the primary focus had shorter overall survival than those with CDKN2A deletions in the metastatic focus (median 37.35 months vs. 45.67), but the difference was not statistically significant (P = 0.838)." (PMID 39323996, 2024). "It is worth noting that the data presented on the A549 non-small cell lung cancer cell line correspond to a lung adenocarcinoma cell line, which specifically carries KRAS and CDKN2A gene mutation, with KRAS being one of the most commonly observed mutations in LC." (PMID 38674017, 2024). "Clinical data stemming from research conducted at the Memorial Sloan Kettering Cancer Center revealed an association between the absence of CDKN2A expression and a poorer prognosis in stage I lung adenocarcinoma." (PMID 39323996, 2024). "Accumulate evidence demonstrated that CDKN2A is common in cerebrospinal fluid (CSF) samples of lung adenocarcinoma patients with central nervous system (CNS) metastases, and concurrent CDKN2A with EGFR-sensitive mutations indicated inferior median intracranial PFS (iPFS)." (PMID 35614407, 2022). "The heatmap reveals that HNRNPLL|53258|AT, CA5B|98313|ES, MEGF6|315|ES, and CDKN2A|86000|AP may have positive effects on lung adenocarcinoma while BEST3|23330|AT, TTC39C|44852|AP, AP2B1|40327|AD, LETM2|83399|AT, and MKL1|62348|AP can have adverse effects." (PMID 35004299, 2021). "The role of CDKN2A in lung adenocarcinoma has been investigated previously." (PMID 35004299, 2021). "CDKN2A was also found to be a prognostic factor in lung adenocarcinoma." (PMID 35004299, 2021). "While DeClust-identified subtypes were not more significantly associated with survival in general, DeClust identified a poor prognosis subtype of clear cell renal cancer, papillary renal cancer, and lung adenocarcinoma, all of which were characterized by CDKN2A deletions." (PMID 32111252, 2020). "Therefore, the role of CDKN2A in lung adenocarcinoma was further explored." (PMID 35004299, 2021). "In our study, CDKN2A may have potential oncogenic effects in lung adenocarcinoma." (PMID 29285217, 2017).
lung adenocarcinoma (continued). "Among a total of 200 patients, we identified a cohort of 72 patients with lung adenocarcinoma (LUAD) who were treated with pemetrexed plus carboplatin and had tumor RNA expression data on both the MTAP and CDKN2A genes." (PMID 35379845, 2022). "Homozygous deletion (HD) of CDKN2A and CDKN2B (CDKN2A/BHD) is the most frequent copy‐number variation (CNV) in lung adenocarcinoma (LUAD)." (PMID 35253368, 2022). "Alterations involving ATM, and Cyclin Dependent Kinase Inhibitor 2A and 2B (CDKN2A and CDKN2B) have also been found in KRAS mutant lung adenocarcinomas." (PMID 34944952, 2021). "For instance, Wang and colleagues recently reported a five-autophagy-related signature (ITGB4, NLRC4, ATG9B, CDKN2A, ERO1A) based on overall survival in patients with lung adenocarcinoma." (PMID 34252349, 2021). "Only two clinically actionable genes—CDKN2A and CDKN2B—had lower frequencies of alteration in protocol patients with lung adenocarcinoma." (PMID 32914008, 2019). "In the GSE10072 array, expression levels of CDKN2A, PHLDA2, and SFN are significantly upregulated in lung adenocarcinoma compared to normal lung tissue in several datasets, and NDRG4 is downregulated." (PMID 29285217, 2017). "To our knowledge, CDKN2A EX2, CDX2, HOXA1 and OPCML constitute the strongest lung adenocarcinoma DNA methylation markers identified to date, and we are working on further evaluations of their potential with great anticipation." (PMID 17967182, 2007). "Survival analysis revealed that in patients with stage I lung adenocarcinoma, those who lacked CDKN2A expression had worse overall survival compared with those with normal CDKN2A expression (median 86.63 months vs. not reached, P = 0.008)." (PMID 39323996, 2024). "In patients with stage IV lung adenocarcinoma metastases, those with CDKN2A deletions had a poor prognosis (median 45.67 months vs. not reached), but the difference was not significant (P = 0.12)." (PMID 39323996, 2024). "Knowledge of the roles of CDKN2A and CDKN2B HD in lung adenocarcinoma (LUAD) is scarce." (PMID 35253368, 2022). "In this research, samples of lung adenocarcinoma were interrogated with cuproptosis-related genes, among which high expression of DLD, DLAT, PHDA1, PHDB, and CDKN2A were correlated with poor OS, while high expression of MTF1 was correlated with longer OS compared with the MTF1 low expression." (PMID 36003780, 2022). "The analysis of the effects from each gene expression on survival outcome indicated that 6 genes (AGR2, SPDEF, CDKN2A, CLDN3, SFN, and PHLDA2) play oncogenic roles, and 7 genes (PDK4, FMO2, CPED1, GNG11, IL33, BTNL9, and FABP4) act as tumor suppressors in lung adenocarcinoma." (PMID 29285217, 2017). "The four most highly ranked loci, CDKN2A EX2, CDX2, HOXA1 and OPCML, which show significant DNA methylation even in stage IA tumor samples, merit further investigation as some of the most promising lung adenocarcinoma markers identified to date." (PMID 17967182, 2007). "Thus, we suggest that CDKN2A EX2, CDX2, HOXA1 and OPCML are the top candidates from the 28 tested, and should be validated as DNA methylation markers for lung adenocarcinoma." (PMID 17967182, 2007). "In patients with stage IV lung adenocarcinoma, those who lacked CDKN2A expression in the primary tumor had longer overall survival than patients with normal CDKN2A expression (median 37.35 months vs. 23.61 months), but the difference was not significant (P = 0.119)." (PMID 39323996, 2024). "Using the current tissue collection and 5-fold cross validation, the four most significant loci (CDKN2A EX2, CDX2, HOXA1 and OPCML) individually distinguish lung adenocarcinoma from non-cancer lung with a sensitivity of 67–86% and specificity of 74–82%." (PMID 17967182, 2007).
type 2 diabetes (71 papers, 2009 to 2025). "An interaction between low birth weight and CDKN2A/B risk alleles increases susceptibility to type 2 diabetes." (PMID 41190158, 2025). "Type 2 diabetes, as a complex metabolic disease influenced by multiple genes, has drawn considerable attention regarding the role of CDKN2A as a risk gene." (PMID 38904034, 2024). "Genome-Wide Association Study (GWAS) is generally utilized to compare Single Nucleotide Polymorphisms (SNPs) of the CDKN2A gene between patients with Type 2 diabetes and normal control groups." (PMID 38904034, 2024). "All these studies have demonstrated the significant correlation between the CDKN2A gene and susceptibility to Type 2 diabetes." (PMID 38904034, 2024). "In human skeletal muscle, we observed that markers of oxidative fibers and mitochondria correlated positively with expression levels of PPARGC1A and CDK4 and negatively with expression levels of CDKN2A, a locus significantly associated with type 2 diabetes." (PMID 37395281, 2023). "Recently, Cdkn2a has been linked to obesity and type 2 diabetes in both rodent and human genome-wide association studies." (PMID 37169793, 2023). "Accordingly, loss of function of CDKN2A and p14Arf appear to be involved in obesity and type 2 diabetes." (PMID 35456025, 2022). "Studies across varied ethnicities and geographical locations showed that polymorphisms at the CDKN2A locus are related to type 2 diabetes mellitus development." (PMID 33500527, 2021). "As an illustration, type 2 diabetes risk alleles identified at the CDKN2A/B locus have been implicated in reduced beta cell function." (PMID 32705315, 2020). "Transgenic mice overexpressing CDKN2A/B display decreased islet proliferation, suggesting that the type 2 diabetes risk alleles influence pathology by increasing CDKN2A/B expression." (PMID 32705315, 2020). "The CDKN2A/B locus is associated with risk of cancer, atherosclerotic disease, type 2 diabetes, stroke, aneurysm, periodontitis, Alzheimer's disease, aging, frailty, glaucoma, endometriosis, multiple sclerosis, hypertension." (PMID 30087655, 2018). "CDKN2A/2B encodes two kinase inhibitors, which play an important role in β-cell regeneration, and thus the functional connection to type 2 diabetes is obvious." (PMID 29544538, 2018). "In humans, SNPs near the cell cycle genes CDC123 and CDKN2A have been found to be associated with increased susceptibility to type 2 diabetes." (PMID 29159468, 2018). "Specifically, the type 2 diabetes-associated cyclin-dependent kinase inhibitor 2A, which strongly inhibits the proliferative cyclin-dependent kinase 4 (CDK4), was enriched in PAX4R129W islets whereas it was decreased in PAX4 islets." (PMID 26813254, 2016). "It is noteworthy that an independent SNP in the CDKN2A/B locus near the 9p21 53-kb LD block has been robustly associated with type 2 diabetes." (PMID 25551366, 2014). "Specifically, genetic variants at CDKN2A/B locus have been associated with type 2 diabetes in many ethnic populations." (PMID 24672805, 2014). "Evidence from previous GWA studies suggest cell cycle dysregulation as a common mechanism in type 2 diabetes; for example, type 2 diabetes association signals are found close to the cell cycle regulator genes, CDKN2A/CDKN2B and CDKAL1." (PMID 25211022, 2014). "A number of publications in the last five years confirm and validate that CDKN2A/B is a locus associated with genetic risk of type 2 diabetes development." (PMID 24672805, 2014). "Recent studies showed that single nucleotide polymorphisms mapped in the ANRIL as well as in Cdkn2a locus sequences are linked to several pathologic conditions, including type 2 diabetes." (PMID 24672805, 2014). "The majority of the potentially novel results were for single PheWAS phenotype-classes, for example, for CDKN2A/B rs1333049 (previously associated with type 2 diabetes in EA) a PheWAS association was identified for hemoglobin levels in AA." (PMID 23382687, 2013).
type 2 diabetes (continued). "For CDKN2A/B rs1333049, a SNP previously associated with type 2 diabetes, coronary artery disease, and hypertension in European-descent populations p<0.01 associations were identified for the phenotype-class of Hemoglobin." (PMID 23382687, 2013). "A genomic region near the CDKN2A locus, encoding p16INK4a, has been associated to type 2 diabetes and atherosclerotic vascular disease, conditions in which inflammation plays an important role." (PMID 22403661, 2012). "We observed a significant association between CDKN2A/B rs10811661 and type 2 diabetes (OR: 1.26, P = 1.8*10−4) in Chinese." (PMID 20161779, 2010). "Besides, it is worth mentioning that CDKN2A is not only associated with Type 2 diabetes, but also with diabetic nephropathy and gestational diabetes." (PMID 38904034, 2024). "Additionally, variations in CDKN2A expression have been linked to the regulation of T cell phenotypes in AS and type 2 diabetes." (PMID 39553847, 2024). "In addition, type 2 diabetes (T2D) single nucleotide polymorphisms (SNPs) in Hhex (rs11187146) and Cdkn2a/b (rs1333049) were linked as being as additive risk factors in likelihood of developing and dying from breast cancer in an American patient cohort." (PMID 37398663, 2023). "Furthermore, genome‐wide association studies (GWAS) have linked CDKN2A to many age‐related pathologies, including susceptibility to frailty and increased risk of coronary artery disease, myocardial infarction, type 2 diabetes, and Alzheimer's disease." (PMID 29143441, 2018). "Notably, lncRNA ANRIL shown upregulated in our study was also linked to CDKN2A/B, a strong type 2 diabetes risk gene variant." (PMID 30139387, 2018). "Our results may reflect that the association of the CDKN2A/B locus with type 2 diabetes and cardiovascular disease depends on gene products other than p16INK4a encoded by this high risk genomic region, such as p19ARF or p15INK4b." (PMID 22403661, 2012). "GWASs have recently described novel type 2 diabetes susceptibility loci, including several previously unknown genomic regions, such as CDKN2A/B and CDKAL1." (PMID 20161779, 2010). "In this context it is important to notice that polymorphisms in the neighbouring CDKN1C have been associated with increased birth weight, and that variation in the CDKN family (CDKN2A/B locus; chromosome 9p21) has been associated with type 2 diabetes in recent GWAS- and GWAS-replication studies." (PMID 19516902, 2009). "We identified fourteen type 2 diabetes-associated genes discovered by the first waves of GWAS for which there was little prior evidence of their potential role in diabetes (Adam30, Adamts9, Camk1d, Cdc123, Cdkal1, Cdkn2a, Cdkn2b, Ext2, Hhex, Ide, Jazf1, Lgr5, Thada and Tspan8)." (PMID 23442068, 2013). "Thus, as with the Hhex-Ide locus, these studies cannot distinguish whether Cdkn2a or Cdkn2b is the causative gene, and actually suggest a role for both in the development of type 2 diabetes." (PMID 23442068, 2013). "Within the Asian population, the correlation between CDKN2A and Type 2 diabetes has been extensively studied in various countries and regions, including but not limited to Japan, China, India, and Thailand." (PMID 38904034, 2024). "Close relationship has been found between the CDKN2A/B locus and a variety of well-known disorders such as atherosclerotic disease, type 2 diabetes, stroke, periodontitis, aging, and hypertension." (PMID 35186169, 2022). "Some studies explored the interaction of genes and fetal malnutrition or birth size/weight in type 2 diabetes risk (K121Q, HHEX, CDKN2A/2B, etc.)." (PMID 33353041, 2020).